TIGIT (T cell immunoreceptor with Ig and ITIM domains)
Diseases named in the same sentence as TIGIT in open-access papers (continued):
Sharing a sentence is not in itself a finding about the gene and the disease.
lung cancer (39 papers, 2019 to 2025). A malignant neoplasm involving the lung. "TIGIT expression has been associated with poor prognosis in non–small cell lung cancer, particularly in combination with PD-L1 expression, as well as in muscle-invasive bladder cancer, where it serves as a potential predictive biomarker of an inferior response to chemotherapy." (PMID 40822998, 2025). "TIGIT is expressed in various lung cancers, including NSCLC, and overexpression of TIGIT/CD155 is an unfavorable prognostic factor in lung adenocarcinoma." (PMID 40510353, 2025). "Radiotherapy combined with NBTXR3 plus simultaneous blockade of three immune checkpoint receptors, PD1, LAG3 and TIGIT, was evaluated in an animal model of lung cancer resistant to anti-PD1 therapy." (PMID 40277786, 2025). "Inhibition of the TIGIT pathway sustainably enhances the cytotoxic effects of NK cells against lung cancer cells, thereby offering a crucial theoretical basis for advancing clinical immunotherapeutic strategies." (PMID 40463500, 2025). "Studies show that antagonistic antibodies against TIGIT, when used with PD-1 inhibitors, effectively curb lung cancer growth in immunocompetent mice." (PMID 39726592, 2024). "Clinical trials are ongoing to investigate the efficacy of targeting LAG3, TIM-3, and TIGIT in lung cancer." (PMID 38474400, 2024). "Otherwise, high serum levels of CD112 correlated with clinical stage, tumor size and metastatic status, but was not considered a significant predictor of progression-free survival in lung cancer, probably derived from its weak interaction with TIGIT." (PMID 39267111, 2024). "In this review, we explore the biology of the TIGIT checkpoint and its potential as a therapeutic target in lung cancer." (PMID 37325585, 2023). "In this study, the effect of TIGIT blockade on the anti-tumor activities of human ex vivo-expanded NK cells was evaluated in vitro in the context of lung cancer." (PMID 37345049, 2023). "PM21-NK cells were co-cultured with 2D A549 lung cancer cell monolayers at a 0.33:1 NK:A549 cell ratio in the presence of anti-TIGIT antibodies or isotype controls and cytotoxicity was measured with a live-cell imaging assay." (PMID 37345049, 2023). "Anti-TIGIT strategies are being investigated in other human malignancies aside from lung cancer, with promising initial results." (PMID 37109579, 2023). "Recent studies have highlighted the importance of TIGIT in regulating immune cell function in the tumor microenvironment and its role as a potential therapeutic target, especially in the field of lung cancer." (PMID 37109579, 2023). "The importance of TIGIT as a target for immune-checkpoint inhibition in lung cancer is becoming more and more clear as clinical trials continue to progress and provide results on the therapeutic effectiveness of anti-TIGIT mAbs." (PMID 37109579, 2023). "Here, we provide a review of the recent advances in TIGIT-blockade in lung cancer, and also insights on TIGIT relevance as an immunohistochemical biomarker and its possible theranostic implications." (PMID 37109579, 2023). "In this study we demonstrate that T and NK cells within both the blood and tumours of renal and lung cancer patients seldom co-express TIGIT and CD226, suggesting that within certain tumours TIGIT acts predominantly independently of CD226 cis interactions." (PMID 37596248, 2023). "The data presented intimates the role of TIGIT as a contributor to lung cancer progression and a candidate biomarker for immunotherapeutic targeting." (PMID 37325585, 2023). "TIGIT blockade increased PM21-NK cell cytotoxicity against 3D lung cancer spheroids and prevented PVR-mediated dysfunction after exposure to tumor spheroids." (PMID 37345049, 2023). "Several anti-TIGIT monoclonal antibodies of the IgG1 isotype are currently being evaluated in lung cancer clinical trials." (PMID 37109579, 2023).
lung cancer (continued). "Other phase I/II studies are underway in lung cancer exploring combinations of humanised IgG1 anti-TIGIT (Domvanalimab/AB154) in combination with anti-PD1 agent Zimberelimab (EDGE-Lung, NCT05676931) and anti-adenosine agent Etrumadenant (AB928) (NCT04791839)." (PMID 37325585, 2023). "Immunodeficient mice were subcutaneously inoculated in the flanks with both untransduced TC-1 lung carcinoma cells (referred to as WT TC-1) and TC-1 cells overexpressing either mouse or human TIGIT." (PMID 37799715, 2023). "While promising results were observed in patients with lung cancer, the role of TIGIT in oral squamous cell carcinoma (OSCC) as a biomarker as well as a therapeutic target remains elusive." (PMID 36551992, 2022). "More importantly, almost all of the available clinical data on anti-TIGIT antibodies is from lung cancer patients, and the majority of ongoing clinical studies are also in lung cancer patients." (PMID 34572463, 2021). "Our data demonstrated that most of the Treg cells in the pleural effusions of lung cancer patients were characterized by high expression levels of TIGIT (an immunosuppressive molecule)." (PMID 32052078, 2020). "TIGIT depletion significantly delayed the growth of LLC1 lung carcinoma compared to WT controls." (PMID 38279870, 2024). "However, there are limited studies assessing the role of TIGIT on the function of human NK cells (hNK), particularly in lung cancer." (PMID 37345049, 2023). "Interestingly, many lines of evidence suggest that TIGIT is important in reducing adaptive and innate immunity towards malignancies, and anti-TIGIT mAbs have shown promising results in the field of lung cancer." (PMID 37109579, 2023). "Many other human anti-TIGIT mAbs are currently being tested in Phase I/II clinical trials in combination with PD-1/PD-L1 blockade or chemotherapies for the treatment of advanced lung cancer." (PMID 37109579, 2023). "Anti-TIGIT antibodies currently in lung cancer clinical trials." (PMID 37109579, 2023). "Furthermore, other immunotherapies such as dual–ICIs, cancer vaccine, ACT and T–cell immunoreceptor with Ig and ITIM domain (TIGIT) blockade also showed clinical value in selected lung cancer patients." (PMID 36532038, 2022). "The synergistic effect of combination therapy involving PD-1 inhibitors and TIGIT inhibitors in mouse models suggests that it may be possible to treat lung cancer patients with upregulation of both PD-1 and TIGIT." (PMID 35659630, 2022). "The lung cancer model treated with NBTXR3 metal nanoparticles plus microwave irradiation, anti-PD-1, anti-TIGIT and anti-LAG-3 demonstrated increased efficacy compared to a protocol that excluded LAG-3 blockade." (PMID 40277786, 2025). "Our data have demonstrated that TIGIT+CD8+ T cells in LUAD are functionally exhausted; however, the potential role of TIGIT in regulating lung cancer pathogenesis remains elusive." (PMID 38279870, 2024). "This study was designed to provide a more detailed understanding of TIGIT function on activated human NK cells derived from healthy donors prior to, and after, exposure to PVR-expressing lung cancer spheroids." (PMID 37345049, 2023). "This differential in TIGIT expression between Tregs and CD4 and CD8 T cells is also maintained in the tumor microenvironment, demonstrated by higher levels of 5 different lung cancer dissociated tumor cultures (DTC), vs normal peripheral cells." (PMID 38022590, 2023). "Here, we show that TIGIT and CD226 are infrequently co-expressed on both peripheral blood and particularly so on tumour infiltrating lymphocytes in renal and lung cancer." (PMID 37596248, 2023). "In lung cancer patients, miR-4443 has been shown to potentially affect the expression of CTLA-4 and TIGIT, and the overall survival of patients by regulating the ZC3H12D-hsa-miR-4443-ENST00000630242 axis." (PMID 36765782, 2023).
lung cancer (continued). "Moreover, in a preclinical murine model of lung cancer, TIGIT blockade can increase the efficacy of adoptive transfer therapies with engineered T cells, suggesting that, besides anti-PD-1 or PD-L1, the specific TIGIT targeting may be combined to other anti-cancer therapies." (PMID 37629138, 2023). "We combined NBTXR3-enhanced localized radiation with the simultaneous blockade of three different checkpoint receptors: PD1, LAG3, and TIGIT, and tested the treatment efficacy in an anti-PD1-resistant lung cancer model in mice." (PMID 36123677, 2022). "In the PVR-positive A427 lung cancer model, studies have demonstrated that therapeutic strategies targeting KIR2DL5+TIGIT+ NK cells achieve significantly greater efficacy when employing KIR2DL5 blockade compared to TIGIT blockade." (PMID 40463500, 2025). "Of note, PD1 expression was lower than LAG3 and TIGIT in CD8+ T cells, suggesting that LAG3 and TIGIT might be potential targets for alternative immunotherapies in lung cancer CNSm." (PMID 40883281, 2025). "Other nectin-like molecules have also demonstrated clinical importance in lung cancer, such as CD112 and CD113, but CD155 raises as the most representative due to its higher affinity for TIGIT, which increases its importance as a potential target of therapeutic inhibition." (PMID 39267111, 2024). "Clinical trials of immune checkpoint modulators (TIM3, LAG-3, TIGIT, BTLA, and IDO) in lung cancer." (PMID 39726592, 2024). "Collectively, these findings indicate that in 3D spheroid models, TIGIT blockade enhanced the cytotoxicity of PM21-NK cells over time against lung cancer cells without a change in the phenotype of the NK cells." (PMID 37345049, 2023). "Surprisingly, TIGIT blockade also did not affect PM21-NK cell cytotoxicity in short-term assays with 2D lung cancer monolayers." (PMID 37345049, 2023). "For instance, TIGIT and TIM-3 inhibition in mice cooperated to promote an antitumor immune response; dual blockade of TIGIT and LAG3 improved the treatment efficacy in a mouse model of anti-PD-1-resistant lung cancer." (PMID 36189222, 2022). "Thus, exploiting markers like CTLA-4, TIGIT, OX-40, 4-1BB and GITR, which we observed to be highly expressed by TIL-Tregs, can be a potential therapeutic target for the treatment of the lung cancer patients." (PMID 36566320, 2022). "Further studies are needed to deepen our knowledge of TIGIT expression, both in the neoplastic microenvironment and in tumor cells, and its substantial correlation with the PD1/PD-L1 axis, particularly in the field of lung cancer, on which most immunotherapy trials are focused." (PMID 37109579, 2023). "Expanded NK cells were found to be more resistant to TIGIT inhibition, where TIGIT blockade did not increase the anti-tumor activities of PM21-NK cells against K562 cells or lung cancer cells in monolayers, or within the first 24–32 h of spheroid exposure." (PMID 37345049, 2023).
COVID-19 (37 papers, 2020 to 2026). A disease caused by infection with severe acute respiratory syndrome coronavirus 2. "A heterozygous nonsense variant in the TIGIT gene was identified in a patient in Thailand who had severe COVID-19, resulting in lower TIGIT expression in T cells." (PMID 36191906, 2022). "Our results implied, but not confirmed, that the anti-MM immunotherapy may cause immune overstimulation by downregulating T cells exhaustion molecules such as PD-1 and TIGIT, associated with more severe COVID-19 in this subgroup." (PMID 39355257, 2024). "PD-1 and TIGIT on CD8+ T cells might contribute to the risk-stratification of COVID-19 patient prognosis." (PMID 39355257, 2024). "Aside from older individuals, persons with higher levels of pro-inflammatory cytokines, including those with obesity and diabetes, may be at higher risk of TIGIT overexpression and COVID-19 complications." (PMID 32655579, 2020). "In the acute infection phase, we found the frequency of PD-1 and TIGIT on CD8+ T cells was significantly higher in the severe COVID-19 cases, which was negatively correlated with cellular immune response." (PMID 39355257, 2024). "We observed that PWH had increased expression of activation (eg, CD137 and OX40) and exhaustion (eg, PD1 and TIGIT) markers as compared to PWOH during acute COVID-19." (PMID 38408318, 2024). "The results from Shima Shahbaz also showed significant upregulation of TIM-3, VISTA, 2B4, CD160, PD-1, CD39, TIGIT, and Gal-9 on both T cell subsets in COVID-19 patients." (PMID 39355257, 2024). "This study highlights the role of PD-1/PD-L1 and the TIGIT/CD226/CD155/CD112 pathways in COVID-19 patients." (PMID 39764446, 2024). "In our study, we also observed that the expression of inhibitory receptors NKG2A and TIGIT on NKT-like cells increased significantly in pregnant women with COVID-19 compared with PHC group." (PMID 39113896, 2024). "The inflammatory condition due to COVID-19 disturbed the frequencies of the TIGIT+ and TIGIT- FOXP3+ T regulatory cell subsets." (PMID 37604833, 2023). "Stem cell-like memory (TSCM), central memory (CM) and terminal effector* (TE*) CD8+ T cells exhibited reduced TIGIT expression in individuals recovered from severe and critical COVID-19 (Bonferroni-adjusted P-value range 0.01–7.21 × 10−6)." (PMID 36433939, 2022). "In contrast, naïve CD8+ T cells and MAIT cells expressed similar levels between study groups or elevated levels of TIGIT in individuals suffered from severe and critical COVID-19, respectively (Bonferroni-adjusted P-value range 0.04–0.004)." (PMID 36433939, 2022). "The expression of TIM-3 and TIGIT in SARS-CoV-2-specific CD8+ T cells tended to be lower among patients who recovered from mild COVID-19 than among patients with acute severe COVID-19." (PMID 34413488, 2021). "In this study, we analyzed alterations in NK cell subsets within peripheral blood mononuclear cells (PBMCs), along with the surface markers NKG2D and TIGIT, in patients with mild-to-moderate COVID-19 during the Omicron phase of the pandemic, and examined their associations with disease severity." (PMID 40421029, 2025). "PD-1 and TIGIT on CD8+ T cells could be important prognostic factors to stratify prognosis in MM patients with COVID-19." (PMID 39355257, 2024). "Clustering and shared upregulation of glycolytic enzyme encoding genes GALM, GAPDH, GPI, and ALDOA together with HIF1A, and transcripts regulating exhaustion (TIGIT and LAG3) suggested that hypoxia/anaerobic axis is associated with impaired CD8+TM function in COVID-19 BALF." (PMID 37029220, 2023). "Increased CD38 expression in severe COVID-19 CD8+TM was closely clustered with exhaustion-coding genes (LAG-3, TIGIT) suggesting CD38 expression is associated with metabolic reprograming, memory impairment, and cellular exhaustion of CD8+TM in the lung of COVID(+) patients." (PMID 37029220, 2023).
COVID-19 (continued). "The study of the frequency of GZMB, CD107a, CD39, PD-1 and TIGIT-expressing Treg cells did not reveal any distinctive pattern in COVID-19 patients associated either with infection or with disease severity." (PMID 37809093, 2023). "Upregulation of co-inhibitory receptors, including cytotoxic T-lymphocyte–associated protein 4, programmed cell death protein 1, lymphocyte-activation gene 3, and T-cell immunoglobulin mucin-3, including TIGIT, has been reported in COVID-19 patients in other studies." (PMID 36191906, 2022). "Indeed, similar to previous reports, T cells displayed an overall exhausted phenotype, with overexpression of VISTA, TIM3, LAG3, TIGIT, and PD-1 co-inhibitory receptors in COVID-19 patient T cell populations." (PMID 33361110, 2021). "The EM CD4+ T cell subset in COVID-19 even showed a significant decrease of TIGIT expression." (PMID 32983106, 2020). "Furthermore, T cells of malaria patients showed even higher frequencies of PD1 and TIGIT than COVID-19 patients and healthy donors." (PMID 32983106, 2020). "For this reason, we surmise that the unfavorable COVID-19 prognosis is directly correlated with plasma TIGIT levels and that anti-TIGIT monoclonal antibodies could be salutary for COVID-19 patients." (PMID 32655579, 2020). "Finally, in individuals with moderate SARS-CoV-2 infection, 2’-5’-Oligoadenylate Synthetase 1 (OAS1), OAS2, OAS3, and T cell Immunoreceptor with Ig and ITIM domains (TIGIT) were elevated, but these levels significantly decreased with increased COVID-19 severity." (PMID 39928675, 2025). "The observed upregulation of PD-1 and PD-L1, along with increased TIGIT and CD112/CD155 expression in severe cases, suggests that these markers may serve as potential biomarkers for identifying high-risk COVID-19 patients with worse prognosis and the need for more intensive clinical monitoring." (PMID 39764446, 2024). "Moreover, immunotherapy may downregulate the expression of exhausted checkpoints such as PD-1 and TIGIT, leading to T-cell overactivation and severe COVID-19." (PMID 39355257, 2024). "Moreover, immunotherapy may downregulate the expression of exhausted checkpoints PD-1 and TIGIT, leading to T cell overactivation and severe COVID-19." (PMID 39355257, 2024). "Along with hyperinflammation in severe COVID-19, there is overwhelming evidence in the literature pointing towards cytotoxic cell immunosuppression due to upregulation of immune exhaustion markers (PD-1, TIGIT, Tim-3, CTLA-4) as an alternative mechanism to severe disease pathogenesis." (PMID 37033961, 2023). "Thus, we hypothesized that TIGIT+Tregs could play an important role in intensifying COVID-19 severity by hampering the defense mechanisms against nosocomial infections during ICU hospitalization." (PMID 37604833, 2023). "Thus, increased levels of TIGIT might have a protective function against severe lung damage and consequently the development of life-threatening COVID-19." (PMID 36433939, 2022). "Thus, further investigation of the role of TIGIT+ Treg cell subsets in COVID-19 is also warranted." (PMID 34113347, 2021). "Indeed, novel preclinical studies have demonstrated that TIGIT knockdown can reverse premature cellular and immune aging, suggesting that downregulation of this molecule may benefit COVID-19 patients." (PMID 32655579, 2020). "The correlation between COVID-19 severity and T cells’ expression of CD137, Fas, OX40, and TIGIT reflects an increase in T cell differentiation from naïve to effector/memory phenotypes upon SARS-CoV-2 reencounter as severity increases." (PMID 40378227, 2025). "In contrast, patients with moderate COVID-19 exhibited increased TIGIT expression, with a notable rise in both TIGIT+NKG2D+ and TIGIT+NKG2D- cells." (PMID 40421029, 2025). "NK cells from patients with severe COVID-19 internalize DNAM-1 following binding to NECTIN2/CD112, whereas TIGIT inhibits NK cells following its low-affinity binding." (PMID 38674024, 2024).